SNX10 (sorting nexin 10)
Diseases named in the same sentence as SNX10 in open-access papers (continued):
Sharing a sentence is not in itself a finding about the gene and the disease.
liver cancer (3 papers, 2018 to 2025). An epithelial or non-epithelial malignant neoplasm that arises from the liver. "In contrast, SNX10 has been implicated as a tumor suppressor in gastric, colorectal, and liver cancers though its role in PDAC has remained unexplored." (PMID 40810725, 2025). "SNX10 has also been shown to have potential role in liver cancer by suppressing microRNA-30d." (PMID 30002654, 2018).
Sepsis (3 papers, 2017 to 2026). Sepsis is defined as life-threatening organ dysfunction caused by a dysregulated host response to infection. "In summary, SNX10 downregulation mitigated sepsis-induced oxidative stress and pulmonary inflammation by inhibiting the NF-κB/NLRP3 pathway." (PMID 41711764, 2026). "Given that cytokine storm is also an important factor for sepsis and even death in vivo, we therefore examined serum cytokine levels in WT and Snx10-/- mice at 24 an 48 h after L. monocytogenes infection." (PMID 28903313, 2017).
steatosis (3 papers, 2019 to 2022). Increased lipid within the cytoplasm of cells. "This study demonstrates that deficiency of a CMA negative regulator, SNX10, can protect mice from alcohol-induced liver injury and steatosis, providing evidence for SNX10 as a potential therapeutic target for ALD." (PMID 31614437, 2019).
alcoholic fatty liver (2 papers, 2022 to 2025). "SNX10 deficiency enhances the development of alcoholic fatty liver by decreasing the degradation of LAMP2A/PLIN2 in the liver." (PMID 40426851, 2025). "This is in concordance with our data showing that increased expression of SNX10 by diclofenac ultimately led to hepatic steatosis." (PMID 35265214, 2022). "Interestingly, SNX10 knockout mice exhibited significantly ameliorated ethanol-induced hepatic steatosis and injury via inhibition of CTSA maturation, LAMA2A stabilization and, thus, CMA activation." (PMID 35265214, 2022).
colon cancer (2 papers, 2018 to 2022). "In order to investigate the metabolic alternations caused by SNX10 KO, untargeted metabolomics was applied on the colonic tumor tissues of male FVB mice." (PMID 29867114, 2018). "In colon cancer, SNX10 has been proved to regulate expression of a core effector, P21, in tumor suppressing pathways and to affect metabolism of amino acids mediating activation of mTOR by regulating chaperone-mediated autophagy." (PMID 35715463, 2022).
fatty liver disease (2 papers, 2022 to 2025). A reversible condition wherein large vacuoles of triglyceride fat accumulate in liver cells via the process of steatosis. "SNX10 expression is expected to be closely correlated with various fatty liver diseases." (PMID 35265214, 2022).
glioblastoma (2 papers, 2023 to 2025). The most malignant astrocytic tumor (WHO grade IV). "By contrast, elevated SNX10 expression in cervical cancer has been associated with increased invasion and metastasis, and this is associated with a poor prognosis in patients with glioblastoma suggesting that the role of SNX10 in cancer is context-dependent." (PMID 40341994, 2025). "Of the 5 common hits, SNX10 was most highly correlated with poor glioblastoma patient prognosis in clinical data sets when overexpressed and demonstrated GSC-specific essentiality when we interrogated a previously published in silico data set." (PMID 36795488, 2023). "To evaluate the proof-of-principle therapeutic potential of SNX10 in glioblastoma, we performed SNX10 knockdown in 2 patient-derived GSCs using 3 independent shRNAs and implanted cells into the brains of immunocompromised mice." (PMID 36795488, 2023). "Targeting SNX10 expression extended survival of orthotopic xenograft–bearing mice, and high SNX10 expression correlated with poor glioblastoma patient prognosis, suggesting its potential clinical importance." (PMID 36795488, 2023). "Furthermore, SNX10 expression levels negatively correlated with prognosis of glioblastoma patients in TCGA, CGGA and Gravendeel glioblastoma data sets, including in analyses restricted to patients with wild-type IDH1." (PMID 36795488, 2023). "SNX10 is a therapeutic target in glioblastoma and informs poor patient prognosis." (PMID 36795488, 2023). "Taken together, these results show that SNX10 is required for glioblastoma growth in vivo and higher SNX10 expression portends worse prognosis in both glioma and glioblastoma patients, suggesting SNX10 as a potential therapeutic target with clinical utility for glioblastoma patients." (PMID 36795488, 2023). "High expression of SNX10 and poorer prognosis in B-ALL is a trend also observed in cervical cancer and glioblastoma." (PMID 40341994, 2025). "SNX10 expression strongly correlated with IDH1 status, tumor histology, and tumor grade; SNX10 expression was higher in patients with wild-type IDH1 and glioblastoma patients." (PMID 36795488, 2023). "Supporting PDGFRβ regulation by SNX10, a negative correlation between SNX10 expression and glioblastoma patient prognosis was observed in the proneural transcriptional subtype, which is characterized by elevated PDGFR signatures." (PMID 36795488, 2023).
osteosarcoma (2 papers, 2025). A usually aggressive malignant bone-forming mesenchymal neoplasm, predominantly affecting adolescents and young adults. "For example, in osteosarcoma tissues, high expression of SNX10 inhibits the proliferation, migration and invasion of tumor cells." (PMID 40341994, 2025).
rheumatoid arthritis (2 papers, 2021 to 2025). A chronic, systemic autoimmune disorder characterized by inflammation in the synovial membranes and articular surfaces. "However, SNX10 knockout in mice reduces the serum levels of TNF-α and IL-1β, resulting in the suppression of immune inflammation and bone erosion in rheumatoid arthritis." (PMID 33594863, 2021).
acute myelogenous leukemia (1 paper, 2023). "In subsets of acute myelogenous leukemia cells, chromatin architecture is disrupted between SNX10 and the nearby HOXA cluster, suggesting that HOXA-specific enhancers may be repurposed to enhance SNX10 expression." (PMID 36795488, 2023).
alcoholic liver damage (1 paper, 2019). "Moreover, research haa shown that various pathways, such as AMPK-Forkhead box O3 (FOXO3A) axis, sorting nexin 10 (SNX10)/chaperone, ALDH2, cannabinoid receptor 2 can induce autophagy to prevent alcoholic liver damage." (PMID 31159489, 2019).
anemia (1 paper, 2017). A reduction in the number of red blood cells, the amount of hemoglobin, and/or the volume of packed red blood cells. "In contrast, our data show that patients with SNX10-related IARO of Västerbotten type described here have a more severe phenotype, with age at onset in early infancy, presenting with optic atrophy, macrocephaly, frontal bossing, proptosis, and anemia." (PMID 28592808, 2017).
Atherosclerotic lesion (1 paper, 2022). A lesion associated with atherosclerosis, a multifactorial and multipart progressive disease manifested by the focal development within the arterial wall of lesions, that ranges from the development of a fatty streak, plaque progression, and plaque disruption. "Moreover, it has been reported that the level of SNX10 is upregulated in human atherosclerotic lesions." (PMID 35265214, 2022).
brain cancer (1 paper, 2023). A primary or metastatic malignant neoplasm affecting the brain. "Within brain cancer cell lines in this cohort, high SNX10 expression was associated with resistance to a number of multitargeted RTK inhibitors, including pazopanib, tivozanib, and lenvatinib, which each target VEGFRs, PDGFRs, FGFRs, and KIT with varying selectivity." (PMID 36795488, 2023).
breast carcinoma (1 paper, 2025). "For example, SNX10 is identified as a novel breast cancer susceptibility gene, among 13 known genes, and its high-impact variants are potentially carried by 6.1 million individuals worldwide, making it the sixth most common gene associated with breast cancer risk." (PMID 41255976, 2025).
colorectal adenocarcinoma (1 paper, 2024). The most common type of colorectal carcinoma. "Using immortalized Caco-2 cells, which are derived from human colorectal adenocarcinoma as a model, caspase-5 was reported to contribute, along with sorting nexin 10 (SNX10) and the PIKFYVE kinase, to the release of LPS from internalized bacterial outer membrane vesicles into the cytosol." (PMID 38785927, 2024).
edema (1 paper, 2026). An abnormal accumulation of fluid beneath the skin, or in one or more cavities of the body. "SNX10 knockdown mice showed remission of CLP-induced pulmonary edema, hemorrhage, inflammatory infiltration, and thickened alveolar septum." (PMID 41711764, 2026).
epilepsy (1 paper, 2023). A brain disorder characterized by episodes of abnormally increased neuronal discharge resulting in transient episodes of sensory or motor neurological dysfunction, or psychic dysfunction. "SNX10 mRNA expression was upregulated across a panel of patient-derived GSCs from various transcriptional subtypes compared with NSCs by RNA-seq, which we validated by qPCR in GSCs, NSCs, and nonmalignant brain cell cultures derived from epilepsy surgical specimens." (PMID 36795488, 2023).
glioma (1 paper, 2023). A benign or malignant brain and spinal cord tumor that arises from glial cells (astrocytes, oligodendrocytes, ependymal cells). "Consistent with the reduced PDGFRβ levels upon SNX10 knockdown in GSCs, SNX10 expression correlated with a PDGFRβ signature score in glioma patients." (PMID 36795488, 2023). "In the clinical data sets, high mRNA expression of SNX10 portended poor glioma patient prognosis in the TCGA and Chinese Glioma Genome Atlas (CGGA)." (PMID 36795488, 2023). "To better understand the potential clinical relevance of SNX10 in glioma patients, we interrogated clinical glioma data sets in The Cancer Genome Atlas (TCGA)." (PMID 36795488, 2023).
heart failure (1 paper, 2021). Inability of the heart to pump blood at an adequate rate to meet tissue metabolic requirements. "Interestingly, SNX10 expression was associated with BNP level 24 hours after surgery, and the use of BNP for the diagnosis and management of heart failure is well established." (PMID 33594863, 2021).
hepatocellular carcinoma (1 paper, 2022). A malignant tumor that arises from hepatocytes. "Interestingly, aberrant expression of SNX10 has been reported in hepatocellular carcinoma." (PMID 36612066, 2022).
Hypertension (1 paper, 2021). The presence of chronic increased pressure in the systemic arterial system. "One SNP-SNP model met a corrected significance threshold for resistant hypertension using the dominant encoding: rs3801888 (alpha: 0.028; MAF: 0.28) in sorting nexin 10 (SNX10) and rs2858808 (alpha: -1.39; MAF: 0.28) (Bonferroni adjusted LRT p: 0.047; 10,296 SNP-SNP models tested; r2: 0.00037)." (PMID 34086673, 2021).
Hypocalcemia (1 paper, 2015). An abnormally decreased calcium concentration in the blood. "Taken together, these results demonstrate that both the mortality and the mineralization defect observed in Snx10 KD mice were caused by hypocalcaemia and were prevented by calcium supplementation." (PMID 25811986, 2015). "Taken together, these results suggest that the rachitic features of Snx10 KD are due to hypocalcemia caused by the acidification defect in the stomach." (PMID 25811986, 2015). "Similar to osteoclasts, Snx10 KD zymogenic cells exhibit a defect in secretory vesicle formation/maintenance, leading to hypochlorhydria and hypocalcemia." (PMID 25811986, 2015). "The marked hyperparathyoirism of the Snx10 KD mice was corrected in the Snx10 OC KO model, consistent with the hypocalcemia in the former which was prevented by normal gastric acdification in the latter." (PMID 25811986, 2015).
intestinal tumors (1 paper, 2025). "Previous research has shown that SNX10 regulates lysosomal function in both intestinal inflammation and intestinal tumors." (PMID 40426851, 2025).
leukemia (1 paper, 2025). A malignant (clonal) hematologic disorder, involving hematopoietic stem cells and characterized by the presence of primitive or atypical myeloid or lymphoid cells in the bone marrow and the blood. "Therefore, despite the elevated expression levels of SNX10 observed in healthy individuals, its expression pattern and impact in leukemia may be associated with tumor progression, exhibiting a duality in its effects." (PMID 40341994, 2025). "In vivo experiments demonstrated that elevated SNX10 expression accelerated leukemia progression in a mouse model." (PMID 40341994, 2025). "In the present study, both in vivo and in vitro experiments demonstrated that overexpression of SNX10 modified the cell cycle of leukemia cells, suppressed apoptosis, and promoted cell survival." (PMID 40341994, 2025). "SNX10 influences cell proliferation and survival by regulating lysosomal function and vesicle transport, as well as processes such as apoptosis and autophagy, which are particularly critical for leukemia cells." (PMID 40341994, 2025). "In healthy populations, SNX10 is expressed at high levels, while its expression is reduced in patients with B-ALL, which may reflect specific metabolic or transcriptional regulatory changes in leukemia cells." (PMID 40341994, 2025).
malaria (1 paper, 2022). Malaria is a serious and sometimes fatal disease caused by a parasite that commonly infects a certain type of mosquito which feeds on humans. "Among the top 50 genes identified in our RNA-Seq experiment, 5 of them (IFNG, CXCL8, IL3RA, SNX10, MYOF, and RSAD2) had promoter regions that were significantly more accessible in convalescent child patients with malaria than in adult convalescent patients." (PMID 35642634, 2022).
ovarian carcinoma (1 paper, 2025). A malignant neoplasm originating from the surface ovarian epithelium. "In summary, we have demonstrated that SNX10 is specifically expressed in tumor-associated macrophages (TAMs) within ovarian cancer tissues." (PMID 40426851, 2025). "Next, by evaluating the GSE147082 and GSE158937 ovarian cancer single-cell datasets, it was shown that SNX10 is primarily expressed in tumor-associated macrophages (TAMs) rather than tumor cells." (PMID 40426851, 2025). "Since SNX10 causes macrophage lipid metabolism dysfunction, in order to explore whether it also affects the lipid content in ovarian cancer cells, the lipid droplet coating protein (PLIN2) mRNA expression in tumor cells was investigated." (PMID 40426851, 2025). "Based on the finding that SNX10 is mostly expressed in TAMs in ovarian cancer, we aim to investigate its functional role in ovarian cancer biology via macrophages." (PMID 40426851, 2025). "Utilizing a co-culture system, we show that SNX10-dependent macrophage reprogramming enhances ovarian cancer metastasis, chemoresistance, and immune tolerance." (PMID 40426851, 2025). "The results revealed that co-culturing ovarian cancer cells with M0 macrophages, which SNX10 overexpressed (M0-SXN10-EO macrophages), improves their metastatic and invasive abilities." (PMID 40426851, 2025). "Our findings indicate that SNX10 is highly expressed in epithelial ovarian cancer and negatively correlated with prognosis." (PMID 40426851, 2025). "Because M0-SNX10-EO macrophages increase ovarian cancer invasive behavior, we investigated whether SNX10 overexpression impacts macrophage differentiation into M1 or M2 types." (PMID 40426851, 2025). "This suggests that SNX10 influences the prognosis of ovarian cancer via TAMs." (PMID 40426851, 2025). "Additionally, SNX10 differentially modulated PD-L1 mRNA expression in platinum-sensitive and platinum-resistant ovarian cancer cells." (PMID 40426851, 2025). "However, it is unclear whether SNX10 regulates macrophage polarization and influences the biological activity of ovarian cancer." (PMID 40426851, 2025). "SNX10 could be developed as a promising new biological target for ovarian cancer therapy." (PMID 40426851, 2025). "Searching the GEPIA2 and Kaplan–Meier Plotter databases revealed that SNX10 is substantially expressed in ovarian cancer and has a negative correlation with progression-free survival (PFS) or overall survival (OS) of ovarian cancer." (PMID 40426851, 2025).
ovarian tumor (1 paper, 2025). "We discovered that SNX10 expression was positively linked with the infiltration of macrophages, neutrophils, dendritic cells, CD4+T cells, and CD8+T cells in ovarian tumor tissue." (PMID 40426851, 2025).
pancreatic cancer (1 paper, 2025). "This suggests that SNX10 loss contributes to PDAC progression primarily by activating the ERK and STAT3 pathways, major drivers of cell proliferation and survival in pancreatic cancer." (PMID 40810725, 2025). "SNX10’s previously reported role in regulating autophagy suggests that it may similarly affect autophagic pathways in pancreatic cancer and contribute to tumor progression." (PMID 40810725, 2025).
prostate carcinoma (1 paper, 2021). A carcinoma that arises from epithelial cells of the prostate gland. "Then, patients were stratified into two groups: prostate cancer with a known genomic alteration vs. unknown, and the co-expression analysis showed that three lncRNAs: lnc-SNX10-87, lnc-AP1S2-2 and ADPGK-AS1 have significant correlation values with other coding genes." (PMID 33672425, 2021).
pulmonary TB (1 paper, 2022). "The top performing single biomarkers for pulmonary TB versus controls were CALCOCO2, SAMD9L, GBP1, IFITM3, IFIT3 and SNX10." (PMID 35720382, 2022).
resistant hypertension (1 paper, 2021). "One SNP-SNP interaction model, rs3801888 (alpha: 0.028; SNX10) and rs2858808 (alpha: -1.39; STARD13), was identified by the dominant encoding for resistant hypertension." (PMID 34086673, 2021).
valvular heart disease (1 paper, 2021). "In summary, our study is the first to report an association between SNX10 and the valvular heart disease." (PMID 33594863, 2021). "The associations between the SNX10 expression level and the clinical parameter of patients with valvular heart disease." (PMID 33594863, 2021). "Taken together, these results suggest that decreased SNX10 might serve as a risk factor in AF of the valvular heart disease." (PMID 33594863, 2021). "Decreased SNX10 might serve as a potential risk factor in AF of the valvular heart disease." (PMID 33594863, 2021). "Moreover, we firstly reported the association between SNX10 and the valvular heart disease." (PMID 33594863, 2021). "SNX10 was negatively associated with BNP level 24 hours after surgery, suggesting its potential value as a prognostic marker for the valvular heart disease." (PMID 33594863, 2021). "Strong staining for SNX10 was detected in the normal human tissue, and lower expression was observed in the myocardial tissue from the patients with valvular heart disease." (PMID 33594863, 2021). "In the present study, we investigated the relationships between the SNX10 expression and AF as well as the fibrosis degree in valvular heart disease." (PMID 33594863, 2021). "In our study, SNX10 expression was significantly negatively associated with the level of the fibrosis degree, LA diameter, and RA diameter, suggesting that SNX10 may be involved in AF by affecting cardiac remodeling in the valvular heart disease." (PMID 33594863, 2021). "Thus, our data suggests that SNX10 might be a potential prognosis marker for the valvular heart disease." (PMID 33594863, 2021).